ID1 (inhibitor of DNA binding 1)
Diseases named in the same sentence as ID1 in open-access papers (continued):
Sharing a sentence is not in itself a finding about the gene and the disease.
head and neck cancer (2 papers, 2014 to 2021). A primary or metastatic malignant neoplasm affecting the head and neck. "Subsequently, OCT-4-induced synergistic action of ID1 and NF-κB triggers the expression of important head and neck cancer stem cell markers, BMI-1 and CD44." (PMID 33442406, 2021). "This subpopulation is relevant to both Id1 and NF-κB subunit p65 which are frequently expressed in head and neck cancer including OSCC." (PMID 24572994, 2014). "We have shown in our previous study that the Id1 and NF-κB genes are upregulated in approximately 60–70% of head and neck cancer specimens by microarrays and immunohistochemistry analyses." (PMID 24572994, 2014). "Approximately 60% of head and neck cancer specimens are positive for Id1 and NF-κB proteins." (PMID 24572994, 2014). "Our recent studies indicate that head and neck cancer including OSCC is characterized by the expression of Id1 and NF-κB in the majority of clinical patients by microarrays and cancer cells, rich in these two proteins are by nature aggressive and have poor clinical outcomes." (PMID 24572994, 2014).
Hypertension (2 papers, 2015 to 2020). The presence of chronic increased pressure in the systemic arterial system. "Overproduction of BMP4 is pro-inflammatory in vascular cells and has been linked to hypertension and increases ID1 expression." (PMID 32759460, 2020).
Insulin resistance (2 papers, 2019 to 2020). Increased resistance towards insulin, that is, diminished effectiveness of insulin in reducing blood glucose levels. "It was found that loss of the ID1 gene leads to increases in expression of genes which promote fatty acid oxidation, with id1−/− mice also exhibiting reduced insulin resistance and fat mass while on a high fat diet, and increased oxygen consumption compared to wild type mice." (PMID 30846834, 2019).
insulinoma (2 papers, 2013 to 2023). "Both ID1 and ID3 were upregulated by high glucose in cultured human pancreatic islets or insulinoma cells." (PMID 37863933, 2023).
Intellectual disability (2 papers, 2019). "Through Northern Finland Intellectual Disability (NFID) Cohort, we could identify a carrier of de novo nonsense mutation in TET2 (NM_001127208.2:c.1471C>T, NP_001120680.1:p.Gln491Ter; hereafter individual Id1 with TET2X mutation)." (PMID 30890702, 2019).
ischemia (2 papers, 2015 to 2017). A hypoperfusion of the BLOOD through an organ or tissue caused by a PATHOLOGIC CONSTRICTION or obstruction of its BLOOD VESSELS, or an absence of BLOOD CIRCULATION. "In the CA1 region of the ischemia groups, positive ID1 immunoreactivity was detected until 2 days post-ischemia." (PMID 25503067, 2015). "In the ischemia groups, the ID1 protein level was slightly decreased at 2 days following I-R compared to that of the sham-operated group; however, the ID1 protein level was significantly decreased 5 days following I-R compared to that of the sham-operated group." (PMID 25503067, 2015). "In the ischemia groups, ID1 immunoreactivity was barely changed upon I-R." (PMID 25503067, 2015). "The results provided herein therefore support the possibility that the e-sEV-mediated activation of the TGFβ1/ALK1/ID1 cascade may provide a fine tuning angiogenic response which balances the vascular remodeling process and protects muscles against ischemia-induced damage." (PMID 28811546, 2017). "In summary, these results indicate that immunoreactivity and protein levels of ID1 and ID4 are distinctively altered following transient cerebral ischemia only in the CA1 region, and that the changes in ID1 and ID4 expression may relate to the ischemia-induced delayed neuronal death." (PMID 25503067, 2015). "In order to identify the cell types of non-pyramidal ID1+ and ID4+ cells, double immunofluorescence staining was performed for ID1/GAD67, ID4/GFAP and ID4/Iba-1 in the hippocampal CA1 region at 5 days post-ischemia." (PMID 25503067, 2015).
malaria (2 papers, 2017). Malaria is a serious and sometimes fatal disease caused by a parasite that commonly infects a certain type of mosquito which feeds on humans. "Given that gestational age at delivery is a strong predictor of infant birth weight and is itself affected by malaria exposure during pregnancy, gestational age at delivery may be a mediator on the causal pathway of ID1-DBL2x clade and birth weight." (PMID 28801627, 2017). "However, Hamp1 and Id1 expression were not significantly different between malaria-infected mice treated with anti-activin A/B and isotype control antibodies." (PMID 28893916, 2017).
pancreatic adenocarcinoma (2 papers, 2019 to 2025). "In pancreatic adenocarcinoma, emerging evidence suggests that ID1 contributes to tumor aggressiveness by promoting epithelial-mesenchymal transition (EMT) and conferring resistance to chemotherapy." (PMID 40919143, 2025). "Therefore, this study aims to elucidate how hypoxia regulates ID1 expression in pancreatic adenocarcinoma (PAAD), with a specific focus on post-translational modifications mediated by the E3 ubiquitin ligase TRIM21." (PMID 40919143, 2025).
psoriasis (2 papers, 2005 to 2025). An autoimmune condition characterized by red, well-delineated plaques with silvery scales that are usually on the extensor surfaces and scalp. "Interestingly, several genes with major relevance in psoriasis have been found differentially expressed as a consequence of NAC treatment in the particular epithelial cells included in this study, for example S100A9, ID-1 and Cox-2." (PMID 16001974, 2005).
rectum adenocarcinoma (2 papers, 2022). An adenocarcinoma arising from the rectum. "Heterozygous amplifications of ETS2 and CDK6 in TGCT; CDK6 in GBM; E2F1 and ID1 in rectum adenocarcinoma (READ); and SP1, CDK4, and MDM2 in ACC were all greater than 70%." (PMID 35911954, 2022). "We took ID1 expression as an indicator for active BMP signalling and noggin for inhibited signalling and analysed patient data from the Cancer Genome Atlas (TCGA; cohorts colon adenocarcinoma (COAD) plus rectum adenocarcinoma (READ))." (PMID 34841646, 2022).
schizophrenia (2 papers, 2023 to 2024). A major psychotic disorder characterized by abnormalities in the perception or expression of reality. "Six candidate genes (SFN, KDM5B, MYLK, IRF3, IRF7, and ID1) were identified with diagnostic significance for schizophrenia." (PMID 37113536, 2023). "Furthermore, we established a schizophrenia diagnostic model based on genes associated with cellular senescence, which contain 6 candidate genes (SFN, KDM5B, MYLK, IRF3, IRF7, ID1)." (PMID 37113536, 2023).
serous ovarian cancer (2 papers, 2020 to 2021). "There is a significant correlation between the expression of ATF6 and inhibitor of DNA binding 1 (ID1) in high-grade serous ovarian cancer tissues." (PMID 33912571, 2021). "Moreover, we found a significant correlation between the expression of ID1 and ATF6 in 1104 high grade serous ovarian cancer tissues, and that patients with the high expression of ID1 or ATF6 were resistant to platinum treatment and had the poor overall survival and progression-free survival." (PMID 32080166, 2020).
thymic lymphomas (2 papers, 2009 to 2012). "Although Id1 transgenic mice consistently develop large thymic lymphomas, the addiction to diverse aspects of Notch activity varied significantly depending on the existence of other genetic or epigenetic alterations in each tumor." (PMID 22393458, 2012). "When Hes1 transgenic mice were crossed with these mice, the resulting trans-heterozygotes expressing both Hes1 and Id1 developed thymic lymphomas at 100% frequency within 25 weeks and with a median onset of only 14 weeks." (PMID 19688092, 2009). "Previous studies have also shown that expression of Id1, a naturally occurring inhibitor of E proteins, leads to a high incidence of thymic lymphomas in mice." (PMID 19688092, 2009).
thyroid tumor (2 papers, 2013 to 2016). A benign or malignant neoplasm affecting the thyroid gland. "Overexpression of ID1 enhances metastatic potential human thyroid tumors, which lets the thyroid tumor cells acquire the mesenchymal features." (PMID 26662959, 2016). "In a recent microarray analysis, we found CDH6 as a target of Id1 in aggressive thyroid tumor cells." (PMID 24069422, 2013). "Among the Id1 target genes, the Cadherin-6 (CDH6, also known as K-Cadherin) was strongly induced by Id1 in thyroid tumor cells." (PMID 24069422, 2013). "We recently showed that RUNX2 is a crucial mediator of the Id1 aggressive phenotype in thyroid tumor cells." (PMID 24069422, 2013). "Recently, we found Cadherin-6 (CDH6, also known as K-CAD) highly expressed in thyroid tumor cells that display mesenchymal features and aggressive phenotype, following the overexpression of the transcriptional regulator Id1." (PMID 24069422, 2013). "Further, we showed that the transcription factor RUNX2, also a target of Id1, is a crucial mediator of the Id1 pro-invasive function in thyroid tumor cells." (PMID 24069422, 2013). "Recently, we have shown that the aggressive phenotype induced by the transcription regulator Id1 in thyroid tumor cells is accompanied by acquisition of mesenchymal features and by deregulation of over 400 genes, most of which are known to be deregulated or partake in the EMT program." (PMID 24069422, 2013).
alopecia (1 paper, 2023). Hair loss usually from the scalp. "There was no significant reduction of hepatic hepcidin and Id1 mRNA levels and no evident improvement in alopecia." (PMID 37690687, 2023).
angioma (1 paper, 2021). "Recent studies suggest that ID-1 knock-down in endothelial cells derived from angioma inhibits proliferation and induces apoptosis by inhibiting PI3K/Akt/mTOR signaling." (PMID 34440702, 2021).
angiomyolipoma (1 paper, 2017). A neoplasm with perivascular epithelioid cell differentiation often associated with tuberous sclerosis. "We used a genetic strategy for cell-specific depletion of Tsc1 in the mouse embryo NT because expression of ID1 and ID3 was suppressed in angiomyolipoma cells in N-medium, Id proteins as well as high level of Hes1 prevent neurogenesis in NT50, 51, and Id3 and Hes1 are regulated by Notch154." (PMID 29184052, 2017).
Arthritis (1 paper, 2014). Inflammation of a joint. "We also detected significantly more Id1 in RA compared to OA and other arthritis SFs by ELISA, which correlates highly with Chemokine (C-X-C motif) ligand 16 (CXCL16) levels." (PMID 24620998, 2014). "We should also note that the expression of Id1 is generally very low in joint tissues in the K/BxN serum transfer arthritis model, apart from peak arthritis times (days 5 to 12)." (PMID 24620998, 2014). "In addition, CXCR6−/− arthritic mice have markedly reduced Id1 expression in the K/BxN serum transfer model of arthritis." (PMID 24620998, 2014). "However, Day 12 CXCR6−/− mice had significantly reduced arthritis and vasculature (data not shown) and completely lacked EC staining for Id1, showing that Id1 and the CXCL16-CXCR6 ligand-receptor pathway are linked and work together to recruit EPCs from the BM to the synovium." (PMID 24620998, 2014). "Finally, using the K/BxN serum induced arthritis model, we found that EC CXCR6 correlated with Id1 expression by immunohistochemistry." (PMID 24620998, 2014). "We believe that analysis of EPC mediated migration using Id1 as a selective and unique EPC marker may be an intriguing strategy for identifying and targeting EPC vascular integration during the course of active arthritis." (PMID 24620998, 2014).
autoimmune disease (1 paper, 2018). A disorder resulting from loss of function or tissue destruction of an organ or multiple organs, arising from humoral or cellular immune responses of the individual to their own tissue constituents. "The present results suggest a novel role of Id1 in BMP-mediated MSCs function, which may contribute to a better understanding of the mechanism of action of MSCs in treating autoimmune diseases." (PMID 30174696, 2018).
B cell lymphomas (1 paper, 2005). "In this respect, it is of interest that targeted expression of Id1 to B-lymphocytes resulted in aberrant B cell development, massive apoptosis, and subsequent development of B cell lymphomas." (PMID 15877825, 2005).
biliary tract cancer (1 paper, 2023). "And similar to ID1 and ID3 proteins, ID2 is overexpressed in biliary tract cancer." (PMID 39130146, 2023).
Cachexia (1 paper, 2018). Severe weight loss, wasting of muscle, loss of appetite, and general debility related to a chronic disease. "While these findings would suggest that ID3 is the dominant ID protein in myoblasts under normal physiological conditions, in disease states where C/EBPβ expression is induced in myoblasts, for example cachexia, both Id1 and Id3 upregulation are likely to contribute." (PMID 30413755, 2018).
carcinoid (1 paper, 2010). "For the 4 unmatched “other” NSCLC tumors, only 1 tumor demonstrated significantly elevated Id1 expression with 20-fold increased Id1 expression versus the normal control noted in a carcinoid tumor." (PMID 20414347, 2010).
cholangiocarcinoma (1 paper, 2021). A carcinoma that arises from the intrahepatic biliary tree (intrahepatic cholangiocarcinoma) or from the junction, or adjacent to the junction, of the right and left hepatic ducts (hilar cholangiocarcinoma). "We have recently observed ID1 associated with a resting state in cholangiocarcinoma and TNBC (Robert Benezra 2020, “ID1 expression in resting cancer stem cells”, unpublished)." (PMID 34031428, 2021).
cholesteatoma (1 paper, 2024). A pathologic process characterized by the proliferation of keratinizing squamous epithelium resulting in the accumulation of keratin and cells in the middle ear and/or mastoid. "It is known that NF-κβ acts through a pathway with Ki-67 (the inhibitor of the DNA binding protein 1 (Id1) → NF-κB → cyclin D1 → Ki-67) and activates cell proliferation in human cholesteatoma." (PMID 38535082, 2024).
congenital heart disease (1 paper, 2023). A heart disease that is present at birth. "Indeed, ID proteins are among the most highly regulated downstream targets of BMP/Smad signaling, and their importance was recently reported, as the loss of ID1 and ID3 expression associated with BMPR2 mutations contributed to cardiomyocyte dysfunction in patients with congenital heart disease." (PMID 37298503, 2023).
cutaneous melanoma (1 paper, 2018). A primary melanoma arising from atypical melanocytes in the skin. "Importantly, we found that coordinate expression of Id1 or Id3 with HA synthases HAS2, HAS3, and CD44 is associated with reduced overall survival of cutaneous melanoma patients." (PMID 30297743, 2018). "Consistently, coordinate expression of Id1 or Id3 with HAS2, HAS3 or CD44 significantly correlated with reduced survival of cutaneous melanoma patients." (PMID 30297743, 2018).
dilated cardiomyopathy (1 paper, 2017). Cardiomyopathy which is characterized by dilation and contractile dysfunction of the left and right ventricles. "To bypass embryonic lethality we used Tie2CRE-mediated recombination to conditionally delete Id1 against global Id3 ablation (Id cDKOs), which develops adult-onset dilated cardiomyopathy." (PMID 28596553, 2017).
disc degeneration (1 paper, 2021). "qRT-PCR results showed that the expression levels of ID1, RAP2C, and PTPRK were all significantly higher in NP tissues of the grade IV disc degeneration and high immunity groups." (PMID 34122424, 2021).
esophageal tumor (1 paper, 2014). "Our previous studies demonstrated constitutive activation of the PI3K/AKT pathway in esophageal tumor tissues and its regulation by Id1 (inhibitor of differentiation or DNA binding)." (PMID 25344912, 2014).
gout (1 paper, 2014). A condition characterized by painful swelling of the joints, which is caused by deposition of urate crystals. "Id1 is expressed and secreted in SFs, and can be measured in RA, OA and other disease SFs (two gout, one seronegative spondylitis, and one lupus SF)." (PMID 24620998, 2014).
Hodgkins lymphoma (1 paper, 2018). A heterogeneous group of malignant lymphoid neoplasms of B-cell origin characterized histologically by the presence of Hodgkin and Reed-Sternberg (HRS) cells in the vast majority of cases. "Concerning the association between the two oncoviruses (EBV and HPV) and Id-1 gene, which is overexpressed in several human carcinomas, it has been reported that LMP1 onco-protein of EBV upregulates the expression of Id-1 but not FoxO3a in human Hodgkin’s lymphoma cells." (PMID 30035100, 2018).
insomnia (1 paper, 2021). A sleep disorder characterized by difficulty in falling asleep and/or remaining asleep. "Except for the reported findings, we found one set of genes including ID1, ID2, and ID3 was significantly enriched in biological processes of the circadian rhythm and speculated that insomnia in some PCOS patients may due to the abnormal expression of these genes." (PMID 34113617, 2021).
intestinal cancer (1 paper, 2019). "ID1/ID1 might be enriched in the cell-of-origin of intestinal cancer besides being expressed by cancer-propagating cells possessing stemness properties." (PMID 31013771, 2019).
invasive ductal carcinoma (1 paper, 2022). "Expression of ID1 and ID3 was increased in human invasive lobular carcinoma compared with invasive ductal carcinoma, associated with poor prognosis uniquely in patients with invasive lobular carcinoma and correlated with the upregulation of angiogenesis and matrisome-related genes." (PMID 36443709, 2022).
lentivirus infection (1 paper, 2018). Virus diseases caused by the Lentivirus genus. "We next would like to further confirm the negative effect of ID1-induced senescence on chemotherapy in vivo; we established stable ID1 knockdown cell lines in HepG2 through lentivirus infection, and the nude mouse xenograft assay was employed." (PMID 30154433, 2018).
Lewis Lung Carcinoma (1 paper, 2007). "2×106 Lewis Lung Carcinoma (LLC) tumor cells were injected subcutaneously into wild type, Id1-/-, p21-/- and Id1-/-p21-/- mice and tumor growth followed for 12 days." (PMID 18092003, 2007).
liver cirrhosis (1 paper, 2024). "Since ID1 is associated with HCC development, this suggests that an elevated expression of ID1 may play a significant role in the early stages of hepatocarcinogenesis in patients with liver cirrhosis." (PMID 39199400, 2024).
liver failure (1 paper, 2021). A liver disease characterized by the liver losing or has lost all of its function. "The WNT2 and HGF were also verified as targets of ID1 in resection‐induced liver failure in the mouse." (PMID 33635004, 2021).
lobular breast cancer (1 paper, 2020). "Altogether, our comprehensive study of anchorage independence in human ILC cell lines provides mechanistic insights and clinical implications for metastatic dissemination of ILC and implicates ID1 and ID3 as novel drivers and therapeutic targets for lobular breast cancer." (PMID 32661241, 2020).
mammary adenocarcinoma (1 paper, 2015). "Similar experiments were performed with DC and MDSC FACS-sorted splenic populations from the E0771 mammary adenocarcinoma model, and the Id1 expression profile was comparable to the one observed in the B16F10 model." (PMID 25924227, 2015).
memory impairment (1 paper, 2025). "The identified association between elevated transcription levels of CCdc88c and Id1 with memory impairment may enable future rapid clinical diagnosis of synthetic cannabinoid neurotoxicity by detecting peripheral blood expression of these genes (or their encoded proteins)." (PMID 41226463, 2025).